TRBV7-1 (T cell receptor beta variable 7-1 (non-functional))
Description:
Probable non-functional open reading frame (ORF) of V region of the variable domain of T cell receptor (TR) beta chain. Non-functional ORF generally cannot participate in the synthesis of a productive T cell receptor (TR) chain due to altered V-(D)-J or switch recombination and/or splicing site (at mRNA level) and/or conserved amino acid change (protein level). Alpha-beta T cell receptors are antigen specific receptors which are essential to the immune response and are present on the cell surface of T lymphocytes. Recognize peptide-major histocompatibility (MH) (pMH) complexes that are displayed by antigen presenting cells (APC), a prerequisite for efficient T cell adaptive immunity against pathogens. Binding of alpha-beta TR to pMH complex initiates TR-CD3 clustering on the cell surface and intracellular activation of LCK that phosphorylates the ITAM motifs of CD3G, CD3D, CD3E and CD247 enabling the recruitment of ZAP70. In turn ZAP70 phosphorylates LAT, which recruits numerous signaling molecules to form the LAT signalosome. The LAT signalosome propagates signal branching to three major signaling pathways, the calcium, the mitogen-activated protein kinase (MAPK) kinase and the nuclear factor NF-kappa-B (NF-kB) pathways, leading to the mobilization of transcription factors that are critical for gene expression and essential for T cell growth and differentiation. The T cell repertoire is generated in the thymus, by V-(D)-J rearrangement. This repertoire is then shaped by intrathymic selection events to generate a peripheral T cell pool of self-MH restricted, non-autoaggressive T cells. Post-thymic interaction of alpha-beta TR with the pMH complexes shapes TR structural and functional avidity.
Synonyms: TRBV71; TCRBV6S7P; TCRBV7S1
Gene: T-cell receptor variable (V) gene on chromosome 7 (142,332,182 to 142,332,701, forward strand). Ensembl gene ENSG00000211707.
Subcellular location: Cell membrane
Gene Ontology:
Biological process: cell surface receptor signaling pathway
Cellular component: plasma membrane
Homologues: Paralogues in human: TRBV7-2 (78% identical), TRBV7-3 (77% identical), TRBV7-4 (69% identical), TRBV7-6 (69% identical), TRBV7-7 (66% identical), TRBV7-9 (64% identical), TRBV11-2 (59% identical), TRBV11-1 (57% identical), TRBV11-3 (57% identical), TRBV12-4 (52% identical), TRBV12-3 (51% identical), TRBV14 (49% identical), and 39 more.